PPARG (peroxisome proliferator activated receptor gamma)
Diseases named in the same sentence as PPARG in open-access papers (continued):
Sharing a sentence is not in itself a finding about the gene and the disease.
tumor (continued). "Overall, ligand activation of PPARγ in tumour models can result in diversified functional outcome and a better understanding of the exact role of PPARγ in cancer needs to be determined." (PMID 15583697, 2005). "Out of eight benign and 10 borderline tumours, only one tumour in each group showed weak cytoplasmic PPARγ expression." (PMID 15583697, 2005). "In contrast, in some cases of cancer, the expression of PPARγ decreases with the histological grade of the tumour." (PMID 15583697, 2005). "Among eight benign and 10 borderline ovarian tumours, weak PPARγ expression was present in only one tumour in each group." (PMID 15583697, 2005). "Eight out of nine grade 2 tumours studied were positive for PPARγ and the expression varied from a score of 1 to 3 with increased demonstration of nuclear staining." (PMID 15583697, 2005). "Upregulation of PPARγ mRNA levels was found in four of the five (80%) translocation-positive tumours (three FTC and two FTA) analysed." (PMID 15238980, 2004). "To compare PPARγ expression between tumours and NT tissues, we performed quantitative analysis by real-time RT–PCR." (PMID 15238980, 2004). "Overexpression of PPARγ transcripts was detected in 80% (four of five) of translocation-positive tumours." (PMID 15238980, 2004). "The two widely invasive tumours positive for PPARγ had two different components: a follicular area, which stained positive, and an insular area, which was negative." (PMID 15238980, 2004). "Multiple lines of evidence suggest that PPARs, especially PPARγ, play an important role in modulating cell proliferation and tumour growth." (PMID 12454768, 2002). "Immunohistochemistry for PPARγ in tumour specimens of patients with oral SCCa revealed PPARγ production by the tumour cells, which was limited to the well-differentiated areas of the tumours." (PMID 12454768, 2002). "Mechanistically, IMMT loss promotes ATF6α-ATF6β heterodimer formation, whereby ATF6α stabilizes ATF6β protein, enabling ATF6β to engage PPARγ through direct physical interaction and orchestrate redox homeostasis remodeling that sustains tumor cell proliferation." (PMID 42049712, 2026). "Additionally, PPARγ′s modulation of the tumor microenvironment and angiogenesis further supports cancer progression." (PMID 40290121, 2025). "Beyond tumor-intrinsic effects, PPARγ signaling may reshape the tumor microenvironment by polarizing macrophages toward immunosuppressive phenotypes and attenuating dendritic cell-mediated chemokine production, thereby weakening anti-tumor immunity." (PMID 41476922, 2025). "GR signaling promotes tumor-induced atrophy, as GR knockout confers protection; pioglitazone exerts partial anti-inflammatory effects via GR, while the GR antagonist mifepristone (also a partial PPARγ agonist) induces adipogenesis." (PMID 41476922, 2025). "Moreover, MES influences the EGFR and PPARγ pathways, as well as the cell cycle, ultimately leading to tumor growth inhibition." (PMID 40699726, 2025). "Both PPARγ agonists and inhibitors exhibit anti-tumor activities." (PMID 41306968, 2025). "Likewise, in other cancers, many studies suggest anti-tumor effects of PPARγ, but pro-tumor effects are also reported." (PMID 41249163, 2025). "PP5 also plays a tumor-promoting role via positive modulation of PPARγ." (PMID 39776803, 2025). "Additionally, mTORC1 promotes fat synthesis through downstream regulation of PPARγ and Lipin1, further enhancing lipid availability to fuel tumor progression." (PMID 41281744, 2025). "Furthermore, in nude mice with A549 xenografts, CBD (5 mg/Kg) treatment led to the upregulation of cyclooxygenase-2 (COX-2) and PPARγ (an approximate increase of 50%, n = 5) and reduced tumor volume (p < 0.05, n = 5–7)." (PMID 40006844, 2025). "However, the role of PPARγ in BCa progression is dual; while it has tumor-suppressive effects in certain contexts, it also contributes to tumor aggressiveness in other contexts, depending on the tumor microenvironment." (PMID 40806474, 2025).
tumor (continued). "In addition, the engulfment of apoptotic tumor cells rich in cholesterol and lipids activates peroxisome proliferator activator receptor gamma (PPARγ) and liver X receptor alpha (LXRα) in TIDCs." (PMID 41176596, 2025). "Thus, our study revealed that AEVs can not only activate the NF-κB signaling pathway, but also cooperate to inhibit the PPARγ pathway to drive the polarization of macrophages from the protumor M2-like phenotype to the anti-tumor M1-like phenotype." (PMID 41029711, 2025). "Signaling pathway regulation: FABP2 may influence tumor cell differentiation and proliferation through signaling pathways such as Wnt/β-catenin/PPARγ and BMP4/Notch." (PMID 40717587, 2025). "These latter findings suggest that low levels of PPARγ, peroxisomes, and catalase in cancer cells may contribute to tumour progression, and increasing those levels can potentially inhibit cancer growth." (PMID 41373547, 2025). "Given the known involvement of PPARγ in lipid metabolism and differentiation, this modulation may indicate a shift in cellular phenotype upon prolonged exposure to tumor-derived sEVs." (PMID 40282535, 2025). "Therefore, targeting PPARγ and its regulatory networks offers a potential therapeutic strategy to modulate tumor behavior and improve treatment efficacy." (PMID 40806474, 2025). "In the PPAR signaling pathway, the upregulation of PPARγ and its target gene FABP4, along with the significant downregulation of lipid synthesis enzyme SCD, reveals that EA-2 may remodel tumor cell lipid metabolism by activating the PPARγ pathway." (PMID 40906079, 2025). "Our results suggest that in this UC cell line, anti-tumor effects may also be achieved with PPARγ-selective agonists, which may work synergistically with NECTIN4-CAR T cells through surface antigen induction." (PMID 40931013, 2025). "Importantly, IHC revealed nuclear localization of PPARγ in the tumor and in tumor nodules invading adjacent stromal tissues." (PMID 41249163, 2025). "It is widely acknowledged that PPARγ activation facilitates the inhibition of tumor angiogenesis." (PMID 39875357, 2025). "PPARG is a member of the female-biased adipogenesis gene set and a known anti-inflammatory and anti-tumor factor that may contribute to better GBM outcomes in females." (PMID 38895459, 2025). "Conversely, although Myristic acidis is associated with apoptosis via PPARγ activation in late-stage HCC, its depletion in early HCC tissues may reflect tumor-specific adaptations that mitigate lipotoxicity through the upregulation of fatty acid desaturases." (PMID 40500772, 2025). "By simultaneously targeting tumor progression, systemic inflammation, and tissue catabolism, telmisartan exemplifies how selective PPARγ modulation could be therapeutically exploited in cachexia." (PMID 41476922, 2025). "PPARγ activation has been shown to reduce WBC‐mediated inflammation in metabolic disease and certain cancers, raising the question of whether targeted PPARγ agonism could improve outcomes by restoring adipose function and mitigating paracrine tumor support." (PMID 41236441, 2025). "This discrepancy may be attributed to tumor heterogeneity, particularly the variable expression of PPARG across GBM subtypes and cellular compartments." (PMID 41323785, 2025). "RK3 downregulates PPARG expression in tumor cells, leading to a reduction in CCL2 secretion." (PMID 40867316, 2025). "Targeting FABP10 related pathways (e.g., PPARγ, NF-κB) can regulate the tumor microenvironment." (PMID 40717587, 2025). "PAX8::PPARG is primarily associated with follicular-pattern thyroid carcinomas, found in approximately one third of adult FTCs and fvPTCs, and is associated with more extensive capsular and vascular invasion compared to RAS-positive tumours." (PMID 40361475, 2025). "For instance, PPARG may be enriched in specific tumor cell populations, such as GBM stem-like cells, which are underrepresented in bulk tissue analyses." (PMID 41323785, 2025).
tumor (continued). "In addition, in mice with tumor formation in situ, the tumor bodies of the group with high expression of PPARG also had higher expression levels of genes related to fatty acid metabolism, such as ACACA, ACLY and ACSS2 and so on." (PMID 40303293, 2025). "However, accumulating evidence indicates that PPARγ can also facilitate tumor progression in specific contexts, particularly in metabolically adaptive or advanced-stage cancers." (PMID 41476922, 2025). "In summary, the activation of PPARγ exerts beneficial effects in cancer by inhibiting pro-cancerous pathways like Wnt/β-catenin, modulating ER signaling, and improving immune responses within the tumor microenvironment." (PMID 40926269, 2025). "Within the TME, tumor endothelial cells contribute to cancer-associated angiogenesis, while lactic acid promotes M2-like polarization via GPR132, a process regulated by the PPARγ transcription factor, which inhibits GPR132 expression." (PMID 40343509, 2025). "PPARγ exerts tumor-suppressive effects by inhibiting proliferation and inducing differentiation." (PMID 41415282, 2025). "While PPARγ inhibits cancer cell proliferation, its effects on immune modulation may inadvertently support tumor progression." (PMID 40361374, 2025). "Clinically, higher PPARγ expression has been correlated with improved prognosis in certain tumor contexts, and epigenetic derepression of PPARG has been associated with enhanced therapeutic responsiveness, highlighting its potential as a favorable prognostic biomarker and therapeutic target." (PMID 41476922, 2025). "Thus, PPARγ represents both a potential therapeutic ally and a liability, demanding a nuanced and tumor-specific approach." (PMID 41476922, 2025). "PPARγ activation enhances the function of anti-tumor immune cells, such as CD8 + T cells and natural killer (NK) cells, by promoting the secretion of anti-inflammatory cytokines like IL-10 and TGF-β in tumor-associated macrophages." (PMID 40926269, 2025). "PPARγ inhibitors attenuate the pro-inflammatory effects of M1 TAMs and suppress the secretion of pro-tumorigenic cytokines by M2 macrophages, further inhibiting tumor progression." (PMID 41306968, 2025). "For example, inhibiting FABP12 or blocking its interaction with PPARγ/Slug may reverse drug resistance and delay tumor progression." (PMID 40717587, 2025). "Notably, PPARG plays a context-dependent role in cancer by playing both oncogenic and tumour suppressor roles." (PMID 40446016, 2025). "Additionally, the expression of PPARG in tumor tissue has shown significant variability in patients' response to chemotherapy." (PMID 38505269, 2024). "Given the important role of inflammation in cancer, these data suggest that the primary interaction of PPARγ in tumor development may center on its anti-inflammatory activity." (PMID 39195246, 2024). "However, HCT116 cells that were simultaneously overexpressed with ZDHHC6 and co-transfected with shPPARγ or PPARγ C313S mutants exhibited lower rates of tumor growth." (PMID 39148124, 2024). "Moreover, targeting PPARG-related metabolic adaptations in hypoxic tumor cells holds potential for overcoming chemoresistance and improving outcomes in NSCLC." (PMID 39201328, 2024). "The expression of PPARγ has been reported in various tumor tissues and cell lines." (PMID 39199386, 2024).
tumor (continued). "Cluster6 demonstrated partial anti-inflammatory genes and had intrinsic alveolar macrophage marker PPARG, which may interfere with tumor therapy progression through lipid accumulation and fatty acid synthesis." (PMID 38648200, 2024). "Several studies demonstrated that PPARγ can inhibit angiogenesis during the tumor formation." (PMID 39199386, 2024). "However, strong PPARγ expression was detected in the metastatic tumor section treated with a combination of Pioglitazone and Cobimetinib." (PMID 39273076, 2024). "Moreover, our RNAseq-based expression analyses showed a highly significant better overall survival in the group of low PPARG expressing tumours, which was in line with the findings from our own cohort." (PMID 38378472, 2024). "The prognostic impact of PPARG expression was investigated by immunohistochemistry in a case-control study using a matched pair selection of CRC tumours (n = 246) with either distant metastases to the liver (n = 82), lung (n = 82) or without distant metastases (n = 82)." (PMID 38378472, 2024). "In addition, the mice carrying the ZDHHC6 knockdown and mutant PPARγ C313S HCT116 cells exhibited significantly suppressed tumor formation compared to the mice with shControl." (PMID 39148124, 2024). "Moreover, since PPARγ overexpression plays a potential role in tumour immune escape, simultaneous inhibition of PPARγ and immune checkpoints can reshape the immune landscape of liver tumours, and overcome resistance to immune checkpoint blockers." (PMID 38652093, 2024). "Targeting tumor cell death induced by the inhibition of PPARγ combined with immunotherapy may yield favorable outcomes in the treatment of OSCC or other cancers." (PMID 38786003, 2024). "PPARγ, a ligand-dependent nuclear transcription factor, holds significance in tumor development." (PMID 38786003, 2024). "The new findings that tumours with pulmonary metastases show stronger PPARG expressions could thus have prognostic relevance for patients with CRC." (PMID 38378472, 2024). "Taken together, overexpression of POM121 in CRC may inhibit the transcriptional activity of PPARγ, thereby abrogating its tumor suppressor function, e.g., via the cell cycle inhibitor P21 CIP1/WAF1." (PMID 38177114, 2024). "As we found that PPARG expression was not reduced in sun-exposed skin, this supports the idea that the loss of PPARγ expression and activity is a tumor-specific event." (PMID 39195246, 2024). "Moreover, NF-κβ1 activation has strengthened the activation of the Notch1 pathway, and once NF-κβ1 and Notch1 are activated, they inhibit the expression of peroxisome proliferator-activated receptor-γ (PPARγ), and therefore, they enhance tumor proliferation." (PMID 38817387, 2024). "T0901317 can also inhibit tumor cell proliferation through the PPARγ-LXRα-ABCA1 pathway." (PMID 38630355, 2024). "Studies have demonstrated that PPARG is a tumor suppressor in NSCLC." (PMID 39201328, 2024). "TZDs promote insulin sensitivity by activating peroxisome proliferator-activated receptor gamma (PPAR-γ) which has been found to suppress tumor growth in various types of tumor cells by the downregulation of proliferation and insulin resistance and induction of apoptosis." (PMID 39410536, 2024). "Decreased PPARG expression in human lung tumors correlates with poor prognosis, while increased expression influences the production of cytokines crucial for angiogenesis and tumor–stromal interactions." (PMID 39201328, 2024). "Furthermore, treatment with statins and concurrent blockade of PPARγ in TA-AMs can suppress tumor progression and enhance pro-inflammatory immune responses." (PMID 38954021, 2024).
tumor (continued). "The exact role of PPARγ in tumors as oncogenic versus tumor suppressive remains controversial." (PMID 38882990, 2024). "Additionally, there was a synergistic effect when Mw was combined with Rosiglitazone for PPARγ expression, tumor growth, and MMP-9 expression." (PMID 39534596, 2024). "Thus, further research and clinical trials are necessary to comprehensively explore the actions of PPARγ in both tumor and stromal cells and to evaluate the in vivo toxicity." (PMID 38397426, 2024). "PPARγ has influence on diverse metabolic pathways and is present in colorectal epithelial cells, where its activation can stimulate cell differentiation and enhance apoptosis, therefore regulating tumor formation." (PMID 39148124, 2024). "PPARγ exhibits both tumor-suppressive and oncogenic effects in many types of cancers." (PMID 38933330, 2024). "Thus, our data further support the idea that PPARγ acts as a potential tumor suppressor in both human and murine cutaneous SCC formation." (PMID 39195246, 2024). "PPARG might have various functions depending on different stages of tumour progression, especially in relation to pulmonary metastases." (PMID 38378472, 2024). "Increased lactic acid levels (which are indicative of glycolytic metabolism) in the tumour microenvironment have been implicated in reducing PPARγ on intratumoural iNKT, diminishing cholesterol synthesis and IFN-γ production and reducing their anti-tumour immunity efficacy." (PMID 38248845, 2024). "Furthermore, PPARγ activation promotes the reversion of the EMT process in different types of tumor cells." (PMID 37048080, 2023). "This suggests the possible involvement of PPARγ in the anti-tumor effect demonstrated by matcha." (PMID 36582446, 2023). "Targeting Arf1, LPE, or PPARγ may be a feasible new strategy to promote T-cell infiltration in tumors and improve tumor immunotherapy." (PMID 39872623, 2023). "Thus, the manipulation of PPARG expression holds promise as a potential strategy for shaping the immune microenvironment and developing novel therapeutic approaches to combat tumor growth and metastasis." (PMID 38044948, 2023). "Gene expression profiling of B20-sensitive and -resistant tumor endothelial cells also showed that both PPARG and HIF1α expression levels were higher (the difference was significant for HIF1α) in resistant endothelial cells compared with sensitive endothelial cells." (PMID 37100807, 2023). "PPARα and PPARγ have been shown to inhibit tumor progression in several studies." (PMID 37645246, 2023). "Concerning the molecular mechanisms involved in cancer-associated mitochondrial disorganisation, in vitro studies have revealed that tumour-secreted factors alter their function through different mechanisms related to peroxisome proliferator-activated receptor gamma (PPAR-γ) signalling." (PMID 38136400, 2023). "Interestingly, in tumors high tumor abundance, SMAD3 and KLF4 high, and PPARG low expression, were significantly associated with poor prognosis, albeit small sample size." (PMID 38129585, 2023). "Limited evidence suggests that tumor cells may inhibit the activation of PPARγ and C/EBPα in adipocytes through the activation of Wnt pathway, and up regulate preadipocyte factor 1, induce its Reprogramming to fibroblasts, and promote tumor development." (PMID 37305043, 2023). "In addition, PPARγ can induce apoptosis of tumor cells through the exogenous Fas/FasL death receptor pathway or endogenous mitochondrial apoptosis pathway." (PMID 37064872, 2023). "Our findings using mouse xenograft models support the hypothesis that PPARγ activation by rosiglitazone required early intervention to achieve a reduction in tumor growth or progression." (PMID 37816052, 2023). "Promoted by PPARγ agonists, fatty acid up-take and oxygenation may derepress effector T-cells and favor immunologic tumor response." (PMID 38273846, 2023). "These prostaglandins inhibit tumor cell proliferation through PPARγ activation." (PMID 36765904, 2023).